FAXDC2 (fatty acid hydroxylase domain containing 2)
Description:
Promotes megakaryocyte differentiation by enhancing ERK phosphorylation and up-regulating RUNX1 expression.
Synonyms: C5orf4; FLJ13758
Tractability: Antibody: UniProt predicts a signal peptide or a membrane-spanning region.
Gene: Protein-coding gene on chromosome 5 (154,818,492 to 154,859,252, reverse strand). Ensembl gene ENSG00000170271.
Subcellular location: Cytoplasm; Membrane
Gene Ontology:
Molecular function: protein binding; iron ion binding
Biological process: positive regulation of megakaryocyte differentiation; positive regulation of protein phosphorylation; lipid biosynthetic process
Cellular component: cytoplasm; membrane
Genetic constraint (gnomAD): Loss-of-function variants: 37 observed, 35.49 expected, observed/expected ratio (o/e) 1.04, 90% interval 0.8 to 1.37. The upper end of that interval is the gene's LOEUF score, 1.37, which puts it in group 5 of 6, group 1 being the genes least tolerant of losing a copy. Missense variants: 363 observed, 405.96 expected, observed/expected ratio (o/e) 0.89, 90% interval 0.82 to 0.98. Synonymous variants: 152 observed, 153.07 expected, observed/expected ratio (o/e) 0.99, 90% interval 0.87 to 1.14.
Homologues: Orthologues: macaque FAXDC2 (98% identical), chimpanzee FAXDC2 (92% identical), dog FAXDC2 (89% identical), guinea pig FAXDC2 (88% identical), pig FAXDC2 (87% identical), rabbit FAXDC2 (78% identical), rat Faxdc2 (76% identical), mouse Faxdc2 (71% identical), tropical clawed frog faxdc2 (67% identical), zebrafish faxdc2 (60% identical), Drosophila melanogaster CG1998 (45% identical), Drosophila melanogaster CG11162 (34% identical), and 2 more. Paralogues in human: MSMO1 (23% identical), SC5D (16% identical), CH25H (16% identical).
Diseases named in the same sentence as FAXDC2 in open-access papers:
FAXDC2 is named in the same sentence as 20 diseases in open-access papers, as found by Europe PMC text mining. Sharing a sentence is not in itself a finding about the gene and the disease. The quoted sentences say what the papers report.
acute myeloid leukemia (2 papers, 2016 to 2021). Acute myeloid leukemia (AML) is a group of neoplasms arising from precursor cells committed to the myeloid cell-line differentiation. "FAXDC2 (C5orf4) is downregulated in acute myeloid leukemia and is associated with the development of megakaryocytes." (PMID 34745201, 2021). "In contrast, FAXDC2 is significantly downregulated in acute myeloid leukemia and acute megakaryoblastic leukemia." (PMID 27689744, 2016).
leukemia (2 papers, 2016 to 2023). A malignant (clonal) hematologic disorder, involving hematopoietic stem cells and characterized by the presence of primitive or atypical myeloid or lymphoid cells in the bone marrow and the blood. "Its encoded protein, Faxdc2, plays an important role in the development of megakaryocytes, and their dysregulation may contribute to abnormal hematopoietic cell development in leukemia." (PMID 36835651, 2023). "Together, these observations suggest that FAXDC2 participates in megakaryocytic differentiation and its dysregulation may contribute to abnormal hematopoietic cell development in leukemia." (PMID 27689744, 2016). "Together, these results show that FAXDC2 plays a novel role in development of megakaryocytes and its dysregulation may contribute to abnormal hematopoietic cell development in leukemia." (PMID 27689744, 2016).
acute megakaryoblastic leukemia (1 paper, 2016). Acute megakaryoblastic leukemia (AMKL) is a form of acute myeloid leukemia (AML) that occurs predominantly in childhood and particularly in children with Down syndrome (DS-AMKL). "In sharp contrast, FAXDC2 expression was significantly downregulated in peripheral blood cells from AML and acute megakaryoblastic leukemia (AMKL) patients." (PMID 27689744, 2016).
cognitive decline (1 paper, 2018). "Discriminant analysis showed that the best predictors of cognitive decline were EFTUD2, COPZ1, PTPN1, FAXDC2, MLST8 and age." (PMID 29896099, 2018).
Cognitive impairment (1 paper, 2018). Abnormal cognition is characterized by deficits in thinking, reasoning, or remembering. "In addition, the combination of PTPN1, COPZ1, FAXDC2, EFTUD2 and MLST8 is a useful signature for cognitive impairment." (PMID 29896099, 2018).
colon cancer (1 paper, 2024). "Additionally, promoter analysis using data sets from the Encyclopedia of DNA Elements (ENCODE) showed that the H3K4me3 activation mark was present on the promoter of FAXDC2 in normal colon tissue but was completely absent in 2 colon cancer cell lines." (PMID 38488003, 2024).
colorectal cancer (1 paper, 2024). A primary or metastatic malignant neoplasm that affects the colon or rectum. "Highlighting its clinical relevance, FAXDC2 was repressed in Wnt/β-catenin–high cancer xenografts, in a mouse genetic model of Wnt activation, and in human colorectal cancers." (PMID 38488003, 2024). "Consistent with the GEPIA data, in 50 paired normal and tumor samples from colorectal cancer patients, FAXDC2 expression was significantly lower in the tumors compared with the normal tissues." (PMID 38488003, 2024). "Consistent with our xenograft data, FAXDC2 expression was significantly repressed in human colorectal cancers compared with normal colorectal tissue." (PMID 38488003, 2024). "In HCT116 colorectal cancer xenografts that have hyperactive β-catenin and low FAXDC2, we also observed accumulation of C4-methyl sterols lophenol and dihydro-T-MAS." (PMID 38488003, 2024). "To test this, we measured both lophenol abundance and FAXDC2 expression in locally available matched normal and tumor tissues from Wnt-high colorectal cancer patients." (PMID 38488003, 2024). "Most strikingly, these colorectal cancers had markedly elevated levels of lophenol compared with its low abundance in the matched normal tissues with high FAXDC2 levels." (PMID 38488003, 2024). "If FAXDC2 is repressed in most human colorectal cancers, then methyl sterol intermediates should accumulate in those cancers." (PMID 38488003, 2024). "Hence, our identification of FAXDC2 as a Wnt/β-catenin–repressed gene in pancreatic and colorectal cancers is made with high confidence." (PMID 38488003, 2024). "Moreover, in primary human colorectal cancers, the sterol lophenol, regulated by FAXDC2, accumulated in the cancerous tissues and not in adjacent normal tissues." (PMID 38488003, 2024).
lung carcinoma (1 paper, 2021). "The FAXDC2 gene induces megakaryocyte differentiation whereas MYCL encodes a transcription factor concerned in lung cancer." (PMID 34125870, 2021).
ovarian carcinoma (1 paper, 2019). A malignant neoplasm originating from the surface ovarian epithelium. "For RFS of patients with ovarian cancer, SPOCK2 and FAXDC2 were unfavorable prognostic biomarkers but ADAMDEC1, CCNA2, FAM181A, FOXA2, LRRTM1, NEIL3 and XPR1 were favorable prognostic biomarkers." (PMID 31794425, 2019).
pancreatic cancer (1 paper, 2024). "We therefore tested with 3 independent approaches whether FAXDC2 regulates RTK signaling in Wnt-addicted pancreatic cancer models." (PMID 38488003, 2024).
uterine cancer (1 paper, 2021). Primary or metastatic malignant neoplasm involving the uterine corpus and/or the cervix. "For Uterine cancer, FAXDC2 and MYCL gene’s expression changed due to MTUS1 mutation." (PMID 34125870, 2021).
viral infection (1 paper, 2021). "Other low-TE genes include FAXDC2, STYX, and SHOC2 which are involved in the Ras/Raf/Mitogen-activated protein kinase/ERK Kinase (MEK)/Extracellular-signal-Regulated Kinase (ERK) cascade, commonly involved in viral infection, including that of coronaviruses." (PMID 34127534, 2021).
cancer (5 papers, 2019 to 2025). A tumor composed of atypical neoplastic, often pleomorphic cells that invade other tissues. "Blocking Wnt signaling in Wnt-high cancers caused both differentiation and senescence; and this was prevented by knockout of FAXDC2." (PMID 38488003, 2024). "FAXDC2 expression was also markedly enhanced by Wnt inhibition in 4 independent Wnt-high cancer models driven by distinct genetic mutations." (PMID 38488003, 2024). "Fatty acid hydroxylase domain containing 2 (FAXDC2) is a hydroxylase involved in the synthesis of cholesterol and sphingomyelin and downregulated in various types of cancer." (PMID 41186893, 2025). "In this context, our data suggest that one mechanism for RAS-mutant cancers to avoid excess signaling and senescence is to concurrently repress FAXDC2, thereby preventing RTK hyperactivation and inhibiting downstream MAPK signaling." (PMID 38488003, 2024). "Here, taking advantage of a potent Wnt inhibitor and a comprehensive transcriptomic analysis of a Wnt ligand–addicted orthotopic cancer model, we identified a core Wnt/β-catenin–repressed cholesterol biosynthesis enzyme, the 4-methyl sterol monooxidase FAXDC2, that controls this balance." (PMID 38488003, 2024). "To examine whether FAXDC2 was repressed in Wnt-high cancers, we analyzed the data from Gene Expression Profiling Interactive Analysis (GEPIA 2.0)." (PMID 38488003, 2024). "FAXDC2 is repressed in Wnt-high human cancers and leads to an accumulation of C4-methyl sterols." (PMID 38488003, 2024). "Notably, only two genes (EPS8 and FAXDC2) were downregulated in cancer tissues compared with normal controls." (PMID 31794425, 2019). "FAXDC2 is a Wnt-repressed cholesterol biosynthesis enzyme that regulates the abundance of C4-methyl sterol, lophenol, and RTK/MAPK signaling in cancers." (PMID 38488003, 2024). "Our study shows that derepression of FAXDC2 is also a key consequence of Wnt inhibition, suggesting that FAXDC2 may be as important a Wnt target as MYC in Wnt-high cancers." (PMID 38488003, 2024).
tumor (4 papers, 2007 to 2024). "Thus, although tumor proliferation was partially affected by FAXDC2 knockout, the differentiation and senescence response required the increased expression of FAXDC2." (PMID 38488003, 2024).
FAXDC2 also shares sentences with these, for which no sentence is quoted: Alzheimer disease (1 paper); gastric cancer (1); glioblastoma (1); glioma (1); Insulin resistance (1); Parkinson disease (1).